TNF (tumor necrosis factor)
Diseases named in the same sentence as TNF in open-access papers (continued):
Sharing a sentence is not in itself a finding about the gene and the disease.
tumor (continued). "Rg3 is also known to suppress pro-angiogenic (TNF-α) and immunosuppressive cytokine (TGF-β) secretion, which may promote Rg3-induced immunogenic tumor cell death." (PMID 29247225, 2017). "Although TNF-α was first described as a soluble molecule that induces hemorrhagic necrosis in tumor tissues in experimental animals, the following studies reported that TNF-α exerts anti-tumor effects and pro-tumor effects in different circumstances." (PMID 29234328, 2017). "TNFα, a proinflammatory cytokine, is related to the wide spectrum of human diseases including cancer by accentuating EMT, which has been recognized as the first step of tumor invasion and metastasis." (PMID 29109804, 2017). "Apoptotic tumor cell supernatant containing elevated levels of S1P was reported to selectively alter the production of TNF-α and IL-8, while IL-10 production was not altered." (PMID 28367448, 2017). "Like TNF-α, IL-6 facilitates tumor development by promoting the conversion of non-cancer cells into tumor stem cells in vitro via Oct4 gene upregulation expression through IL-6R/JAK/STAT3 signaling." (PMID 28030810, 2017). "In accordance with current dogma, LPS was shown to be a potent MAMP of gram-negative Salmonella, and TNF-α a downstream cytokine alone capable of inducing tumor necrosis and reinforcing a specific adaptive immune response." (PMID 28445131, 2017). "On the other hand, before tumor arrival in the metastatic sites, the primary tumor also produces systemic factors, for example, VEGFA, TGFβ, TNF, and LOX, which induce chemotactic protein expressions like S100A8, S100A9, SAA3 and extracellular matrix remodeling." (PMID 29450136, 2017). "Blocking TNF-α abolished the activity of CM2 in inducing EMT of cancer cells, strengthening the notion that the inflammatory TME plays an important role not only in tumorigenesis, but also in tumor metastasis." (PMID 28170411, 2017). "In contrast, docetaxel-induced TNF-α release from tumor cells appears to be independent of MyD88, since we observed strong docetaxel-induced increases in soluble TNF-α levels in A2780 cells that lack detectable MyD88 expression." (PMID 28915246, 2017). "TNF-α inhibitor not only suppress the metastasis and homing capacity of HCT116 cells but also weakened that of miR-105-overexpressed HCT116 cells through forming less and smaller tumor nodules." (PMID 29238068, 2017). "Indeed, we previously reported that SMCs promote TNFα-mediated cell death in the RMS cell lines Kym-1, RH36, and RH41 and inhibit tumour growth in a Kym-1 xenograft model." (PMID 27966453, 2017). "Also, a trend for elevated hepatic TNFα expression in the LCT and LCT/MCT8 groups was observed in the mice with tumor." (PMID 28915665, 2017). "Furthermore, co-treatment of tumor cells with TGF-β and TNF/IL-1β cytokines cooperatively stimulated expression of MMP9." (PMID 28423685, 2017). "CIK cells’ tumoricidal ability relies on inducing tumor cell apoptosis through direct contact and secretion of cytokines such as IL-2, TNF-a and IFN-γ, and the cytotoxicity of CIK cells is not affected by immune inhibitors such as CsA and FK506." (PMID 28404886, 2017). "Together, these results suggested that lack of Nur77 in macrophages activated EMT and promoted tumor cells migration and invasion through regulating the secretion of the inflammatory cytokine TNF-α." (PMID 28170411, 2017). "Attempts to induce tumor cell death drove intense worldwide research, starting from conventional chemotherapy in the mid-20th century to novel selective approaches, including targeting of TNF (tumor necrosis factor alpha) receptor superfamily members." (PMID 31548531, 2017).
tumor (continued). "TNFα −/− mice survived significantly longer after tumor implantation (p < 0.05), with vagotomy not affecting the prognosis of these animals (p > 0.05)." (PMID 28160574, 2017). "The increased number of tumor macrophages in LL did not result in increased levels of circulating TNF-α." (PMID 28874144, 2017). "Since INOS, COX-2, and, TNF-alpha, and, IL-6 are important factors in the NF-κB pathway, we detected whether PPS could enhance immunostimulatory activities in the tumor microenvironment through regulating these factors and pathways." (PMID 29155869, 2017). "It is found that the anti-tumor effect of APS on H22 tumor-bearing mice might be related to its ability to enhance the expression of IL-1, IL-2, IL-6 and TNF-α and decrease of IL-1040." (PMID 28303957, 2017). "Considering the reported role of TNF-α and its induction via the LPS/ TLR4 axis, we asked whether this central cytokine alone may induce effects similar to LPS in the CT26 tumor model." (PMID 28445131, 2017). "We detected a statistically significant increase in mRNA levels of IFN-γ, granzyme B, TNF-α and perforin 1 in CD8+ TIL from Grail−/− mice, further supporting that Grail controls the effector function of CTLs infiltrated into the tumours." (PMID 28798332, 2017). "IL-1β and TNF-α levels in the cortex and hippocampus did not vary with tumor status or treatment (data not shown)." (PMID 27893434, 2017). "These pathways were not enriched in the HepG2 tumor sample, although four were increased in the HepG2 cell sample (TNFα signaling via NFκB, allograft rejection, IL-6/JAK/STAT3 signaling, inflammatory response)." (PMID 29259231, 2017). "When functioning in a paracrine mode, TNFα can promote inflammation, EMT transition, angiogenesis, as well as modulating the host immune system to create an immune microenvironment more favorable for tumor growth." (PMID 28900035, 2017). "M2 macrophages not only inhibit tumor apoptosis and promote cell proliferation by activating NK-κB, but participated in tumor metastasis by releasing diverse pro-angiogenic factors such as VEGF, FGF2 and TNFα." (PMID 29152078, 2017). "Although our findings do not discount a role for TLR4 in mediating taxane-induced TNF-α production in all tumor cell types, they do suggest a distinct mechanism involving drug entry into tumor cells, with or without an indirect activation of TLR4." (PMID 28915246, 2017). "In addition to its direct effects on cell proliferation, NF-κB can alter tumor growth and progression through activation of its target genes, including IL-6, VEGF, MMP9 and TNF- α." (PMID 28978058, 2017). "Testing whether TGF-β and pro-inflammatory TNF/IL-1β cytokines cooperate in the regulation of MMP9, we found that MMP9 expression was induced only in tumor cells, while fibroblasts expressed high levels of MMP2." (PMID 28423685, 2017). "Median survival of mice bearing CT26 tumours treated with MG- TNFα was significantly increased vs. MG-Empty (p = 0.049), although the apparent reduction in tumour volume was not significant vs. controls (p >0.05)." (PMID 28662099, 2017). "Additionally, the interaction between NF-κB and PARP1 upregulates the level of pro-inflammatory cytokines like tumor necrosis factor α (TNFα) and interleukin 6 (IL6), which will also initiate tumor-promoting inflammation." (PMID 28991194, 2017). "Moreover, both TNF-α and IL-6 in the serum of the C57BL/6J (MyD88+/+) tumor-bearing mice stimulated by APS and LPS were obviously higher than those in NS and ADM groups (P< 0.05)." (PMID 28303957, 2017). "Moreover, TNF and NF-κB pathway activated by TRAIL receptors and FASL, in addition to inducing tumor cell death, eventually will promote proliferation of tumor cells." (PMID 28850071, 2017). "An alternative mechanism is that cancer cells may spread malignant signals to tumor microenvironment and surrounding and/or distant microenvironment, by secretion of cytokines such as TGF-β, TNF-α and VEGFA." (PMID 28881838, 2017).
tumor (continued). "The activation of NF-κB can be triggered by various stimuli including tumor-necrosis factor (TNF), interleukin 1 (IL-1), interleukin 6 (IL-6), endotoxins, carcinogens, tumor promoters, microbial pathogens, free radicals, lipopolysaccharide (LPS), and radiation (UV-light, X-rays, γ-rays)." (PMID 28635648, 2017). "Despite surmounting evidentiary support for apigenin in tumor suppression, there is lack of research regarding its influence on the tumor microenvironment in response to pro-inflammatory cytokines, specifically TNFα." (PMID 28441391, 2017). "In addition, inflammatory cytokines produced by cancer cells (tumor necrosis factor (TNF); interleukin (IL)-1, -6, and -8; and vascular endothelial growth factor (VEGF)) also provide a favorable environment to facilitate tumor growth, invasion, and metastasis." (PMID 29228679, 2017). "Therefore, extravasation of fluorescently labeled liposomes across the endothelium to the tumor compartment after 30 minutes of perfusion under shear flow was measured following HBTAEC treatment with normal media, TCM, or TNF-α." (PMID 28839211, 2017). "TRAIL belongs to the tumor necrosis factor (TNF) family of proteins and induces apoptosis through its receptors DR4 and DR5 in a wide variety of tumor cells, but does not cause toxicity in the majority of normal cells." (PMID 29383187, 2017). "IL-6, similarly to TNF-α, facilitates tumor development, promoting the conversion of noncancerous cells in tumor stem cells." (PMID 28785138, 2017). "Given the importance of multifunctional effector CD8+ T cell immunity in anti-tumor immunity, we measured the Ag-specific CD8+ T cell population and its expression of IFNγ and TNFα, in response to ex vivo OVA257-264 SIINFEKL peptide stimulation, 15 days after tumor implantation." (PMID 28388572, 2017). "Numerous studies have demonstrated that RT leads to increased local production of soluble factors that promote anti-tumor immunity by enhancing activation of local innate immune cells and recruitment of tumor-reactive T cells (e.g., CXCL16, IL-1α/β, IFNγ, and TNFα)." (PMID 28134800, 2017). "Accordingly, inhibition of TNFα using anti-TNFα monoclonal antibodies or TNF receptor fusion protein, such as Etanercept (human TNFR1 extracellular portion and human immunoglobulin G1 (IgG1) Fc) decreased tumor growth and metastasis." (PMID 28900035, 2017). "In this approach, while the biological delivery vehicle is not confined to tumours, TNFα production is restricted via physically targeted radiation induction of the egr-1 promoter to express the TNFα transgene." (PMID 28662099, 2017). "They produce a variety of chemokines and cytokines, such as perforin–granzyme, tumour necrosis factor (TNF) and tumour necrosis factor (TNF)-related apoptosis-inducing ligand (TRAIL) and IFN-γ, by which they are able to inhibit tumour growth and block angiogenesis." (PMID 28404796, 2017). "Moreover, both TNF-α and IFN-γ expression was decreased in the BPA-exposed group, suggesting that the overall tumour microenvironment in this group displays a lesser pro-inflammatory character." (PMID 28874690, 2017). "Tumor necrosis factor (TNF)-related apoptosis-inducing ligand (TRAIL) is a typical member of the TNF superfamily that plays a potential role in the proliferation, differentiation, and apoptosis of tumor cells." (PMID 28178647, 2017).
tumor (continued). "TNF-α, and IL-6 are produced in the microenvironment of the tumor as a result of the nonspecific inflammatory response, which appears to increase c-MET expression." (PMID 28404966, 2017). "In the tumour microenvironment, depletion of FAP+ cells enhances intratumour T cell infiltration, relieves metabolic stress on and delays the exhaustion of CD8+ T cells and enhances TNF and IFN-γ dependent hypoxic killing of tumour cells by T cells." (PMID 28158223, 2017). "Endpoint tumor volumes did not display significant differences in either model upon co-injection of TNF-α." (PMID 28445131, 2017). "In attempt to dissect whether CCL3 influences the tumour milieu, we evaluated the expression of molecules involved in tumour proliferation (EGF, FGF, TGF-β and TNF-α) and angiogenesis (TGF-β1, VEGFa and VEGFb)." (PMID 28881626, 2017). "The pro-inflammatory phenotype of miR-1246 in MSCs was independent of TNFα stimulations and mediated by direct targeting of the tumor-suppressors PRKAR1A and PPP2CB." (PMID 28159925, 2017). "TNF-α is a monocyte-derived cytotoxin that can directly kill tumor cells and has no obvious toxicity to normal cells." (PMID 28086978, 2017). "Macrophages may play a vital role in regulating MIC-1 levels in PC, as the secretion of tumor necrosis factor-α by activated macrophages is restrained by MIC-1 and may influence tumor-killing activity of these cells." (PMID 29203798, 2017). "After pneumonectomy for isolated tumours, histologically normal human lung tissue far from the tumours contains both CD4 and CD8 cells with diverse T cell receptors (TCR) that express CD69, produce TNFα and IFNγ and proliferate in response to influenza virus." (PMID 28475122, 2017). "Whereas anti-PD-1 or anti-TNF alone failed to impair tumor growth, their combination significantly decreased it." (PMID 29273790, 2017). "In our hands, blocking TNFα or IL-6 was unable to prevent the delipidation of adipocytes induced by tumor cells in our co-culture system, suggesting that they are not involved and/or sufficient to explain this paracrine and “acute” delipidation." (PMID 28915700, 2017). "BCG efficacy may be increased by ex vivo tumor antigen-loading and dendritic cell activation as BCG stimulated dendritic cells to secrete TNF-α, which is responsible for phenotypic and functional changes." (PMID 28005163, 2017). "In addition, SM-pretreated NK cells produce significantly higher amounts of TNFα and IFN-γ than their untreated counterpart, when cocultured with their tumor target cells." (PMID 28326081, 2017). "In addition, it was proved that NF-κB signaling, activated through TNF-α, strongly induces migration and accumulation of mesenchymal stem cells at CRC-tumor sites." (PMID 29657291, 2017). "This appears to be the accepted mechanism, by which taxanes promote TNF-α production and release in human macrophages as well as tumor cells, despite the lack of rigorous studies employing tumor cells." (PMID 28915246, 2017). "Absence of TNF-Rp55 or specific blocking of TNF-α led to reduced mucosal injury and inflammation followed by decreased tumor formation." (PMID 28492497, 2017). "We found that wogonoside could reduce the overexpression of TNF-α, TRAF2 and TRAF4 in later stage of tumor, and improved tumor microenvironment." (PMID 28774312, 2017). "The chronic low dose of TNF‐α produced by a number of cancer cells, including RCC, and stromal cells may promote tumour growth and metastasis." (PMID 27297979, 2016). "This could be reversed by anti-TNF-α or anti-IFN-γ therapy, suggesting that FAP+ cells attenuate cellular responses to these cytokines, thus protecting the tumour from cytokine-induced clearance." (PMID 27542276, 2016). "Monocytes/macrophages from tumor-bearing livers, but not normal livers, expressed high levels of TNFα and stimulated S100a8 and S100a9 expression." (PMID 27086923, 2016).
tumor (continued). "Lastly, tumor homogenate supernatants from both SUM149 and DU145 cells were tested by ELISA for TNF-α and IFN-β, both of which could either directly or indirectly have tumoricidal effects." (PMID 27806313, 2016). "A marked increase in tumor cell apoptosis in mice administered with Ad.EPCR probably stems from the combined effect of EPCR-induced specific changes in the genome of MPM cells and increased levels of IFNγ and TNFα in the pleural space." (PMID 27833109, 2016). "In addition, high concentrations of TNF-α have antitumor effects, whereas constant low-level expression of TNF-α can induce a tumor phenotype." (PMID 27081854, 2016). "Inhibition of TNF-α synergized with chemotherapy in PDAC resulted in better pre-clinical responses via killing tumor cells as well as diminishing desmoplasia and inflammation in PDAC tumor stroma." (PMID 27835602, 2016). "Results demonstrated an increased TNF-α positive population in tumors from animals treated with the MAO A inhibitor (row 2), suggesting that MAO A inhibitors upregulate the proinflammatory response and decreased tumor progression." (PMID 26871599, 2016). "Quantitative real-time PCR analysis of total tumor mRNA confirmed an increase of PD-1 transcript levels but not PD-L1 levels or inflammatory cytokines such as tumor necrosis factor α (TNF α) and interleukin-6 (IL-6)." (PMID 27129180, 2016). "Previously, a variety of evidences revealed that pro-inflammatory cytokines, such as TNF-α, IL-1β, TGF-β, could induce metastasis of tumor cells via up-regulating chemokine receptors." (PMID 27356745, 2016). "In this study, the significant decline of IL-4 but no change in the production of IL-12 and TNF-α was observed, which showed the activation of Th1 and NK cells in the tumor sites." (PMID 27246873, 2016). "These pro-tumorigenic cytokines include interleukin (IL)-6, IL-11, IL-21 and IL-22 that activate the STAT3 transcription factor; TNFα, IL-1 and IL-18 that activate NF-κB; and the IL-23 to IL-17 axis of inflammation that activates both STAT3 and NF-κB in tumor cells." (PMID 31051015, 2016). "In addition, neutrophils can inhibit the secretion of tumor necrosis factor-α (TNF-α) and generate vascular endothelial growth factor (VEGF), which has been proposed to play a pivotal role in tumor development and angiogenesis 17,18." (PMID 27438563, 2016). "Therefore, we investigated if the tumor infiltrating Th17 cells also produced other cytokines, notably IFN-γ or TNF-α, as this would provide crucial information regarding their potential function." (PMID 27014625, 2016). "It is known that hemorrhagic necrosis of tumors is not due to direct TNF cytotoxicity on tumor cells but rather due to acute effects on tumor vasculature that is a part of tumor microenvironment." (PMID 27148266, 2016). "The tumor necrosis factor (TNF)-related apoptosis-inducing ligand (TRAIL), a member of the TNF family, is a potent anticancer agent due to its induction of apoptosis in a variety of tumor cell types while having minimal off target effects on normal cells." (PMID 27731378, 2016). "Highly expressed inflammatory factors such as IL‐1β and TNF‐α, markers of inflammatory cells such as CD68 and CD11b, and massive inflammatory cells tracked by fluorescence in necrotic tumor tissue were detected in the tumor tissue of this model." (PMID 27734611, 2016). "Furthermore, the mRNA levels of CD8, TNF-α and IFN−γ were increased following treatment with cisplatin alone in ID8 tumours." (PMID 27147225, 2016). "The mitogenic fraction (PH-I) from the hot water extract of P. heterophylla has significant potent anti-tumor activities against Ehrlich ascites tumor (EAT) cells in mice in vivo but not in vitro by releasing the tumor necrosis factor (TNF)." (PMID 27764127, 2016). "Taken together, the data suggest that TCP-1/TNFα and TCP-1/IFNγ could increase the generation of T lymphocyte in the spleen and enhance the penetration of T lymphocytes into the tumor." (PMID 27342639, 2016).